CTHRC1 (collagen triple helix repeat containing 1)
Diseases named in the same sentence as CTHRC1 in open-access papers (continued):
Sharing a sentence is not in itself a finding about the gene and the disease.
tumor (continued). "The relationship between CTHRC1 levels and clinical pathological parameters was analyzed, and CTHRC1 was identified as a potential biomarker of tumor progression for COAD." (PMID 35307012, 2022). "Mechanistically, by inducing the transcription of downstream target genes (such as cyclin D1, CD44, and c-Myc) and promoting β-catenin nuclear translocation, CTHRC1 ultimately regulates tumor development." (PMID 34702252, 2021). "Through the online database cBioPortal, CTHRC1 genetic alteration information was investigated in various tumor samples from TCGA datasets." (PMID 34702252, 2021). "The analytical results showed that FZD6 and CTHRC1 were both highly expressed in the B cells of tumor samples." (PMID 33777800, 2021). "We show that several genes aberrantly expressed in FP tumors have known tumor promoting biology in humans, including CTHRC1 and NLRC5, and provide support that disruption of the Wnt signaling pathway is a feature of FP." (PMID 33717164, 2021). "Since the highest mutation frequency was observed for CTHRC1 in UCEC, we focused on analyzing mutations in this tumor." (PMID 34702252, 2021). "Various studies indicate that CTHRC1 regulates tumor progression through CTHRC1/Wnt/β-catenin pathways." (PMID 34702252, 2021). "CTHRC1 has been proposed as a pivotal tumor promoter and activator of the planar cell polarity pathway via stabilization of the Wnt-receptor complex." (PMID 34830209, 2021). "Further research has led to the recognition of CTHRC1 as an oncogenic protein with a role in the promotion of tumor growth, invasion and metastasis in multiple malignancies." (PMID 33717164, 2021). "After verification of these genes, 3 hub genes, namely CTHRC1, FNDC1, and INHBA, were found to be upregulated in tumor and associated with poor GC patient survival." (PMID 34968391, 2021). "mRNA vaccines encoding these tumor antigens (THBS2, FSTL3, TNNT1, BGN, CTHRC1, and NOX4) induce a cell-mediated immune response and humoral immune response that are beneficial for efficient clearance of cancer cells." (PMID 35127707, 2021). "Using the STRING tool, we screened the CTHRC1-binding proteins to identify the potential role of the CTHRC1 gene in tumor pathogenesis." (PMID 34702252, 2021). "Results from survival analysis showed that high CTHRC1 expression was associated with poor OS, DSS, DFI, and PFI in KIRP and KIRC, consistent with previous findings CTHRC1 affects tumor growth and invasion and leads to a poor prognosis." (PMID 33628726, 2020). "We examined the CTHRC1 expression differences in multiple tumor tissues and normal tissues via exploring TIMER, Oncomine, and UALCAN databases." (PMID 33628726, 2020). "The influence of CTHRC1 on various events in tumor progression is based on its regulation of various signaling pathways such as TGF-β, Wnt, integrin β/FAK, Src/FAK, MEK/ERK, PI3K/AKT/ERK, HIF-1α, and PKC-δ/ERK signaling pathways." (PMID 32848510, 2020). "Based on the evidence reviewed above, it can be indicated that crosstalk between the canonical Wnt/β-catenin pathway and noncanonical Wnt/PCP pathway and the mutual regulation of Wnt/β-catenin and CTHRC1 accelerate the process of tumor progression." (PMID 32848510, 2020). "Previous studies indicate that CTHRC1 promotes tumor cell progression via influencing specific pathways in various cancer types." (PMID 33628726, 2020). "Several recent studies have identified CTHRC1 as an effectual prognostic biomarker for predicting tumor recurrence or metastasis." (PMID 32848510, 2020). "The cox proportional hazard model of CTHRC1 and six tumor-infiltrating immune cells in KIRP and KIRC (TIMER)." (PMID 33628726, 2020).
tumor (continued). "It should be highlighted that CTHRC1 not only is the result of tumor progression but also plays a predominant regulatory role in the progression and metastasis of many solid tumors." (PMID 32848510, 2020). "CTHRC1 is an extracellular matrix protein that regulates tumor metastasis and the extracellular microenvironment." (PMID 33628726, 2020). "Then, we used TISIDB database to furtherly explore the relationship between CTHRC1 level and 28 tumor immune infiltrating cell subtypes." (PMID 33628726, 2020). "We assessed the correlation between CTHRC1 expression and tumor-infiltrating immune cell gene marker levels in KIRP, KIRC, and CESC tissues by exploring the TIMER database." (PMID 33628726, 2020). "Collagen triple helix repeat containing 1 (CTHRC1) is an extracellular matrix protein that regulates tumor invasion and modulates the tumor microenvironment." (PMID 33628726, 2020). "The mechanism of CTHRC1 in promoting tumor invasion and metastasis varies among different types of tumors." (PMID 32156314, 2020). "study revealed that CTHRC1 recruits Tie2-expressing monocytes into tumor tissues by activating ERK-dependent AP-1 to promote angiogenesis." (PMID 33628726, 2020). "The expression of CTHRC1 is also positively correlated with tumor lymph node metastasis, tumor-node-metastasis (TNM) stage, and disease prognosis." (PMID 32848510, 2020). "Subsequently, the TIMER platform and TISIDB website were chosen to assess the correlation of CTHRC1 with tumor immune cell infiltration level." (PMID 33628726, 2020). "A remarkable effect is that the high expression of CTHRC1 promotes tumorigenesis and development through positive regulation of tumor spread, invasion, migration, adhesion, and metastasis." (PMID 32848510, 2020). "On the other hand, CTHRC1 can also stimulate tumor progression and angiogenesis by increasing the expression of some molecules such as TGF-β, HIF-α, and Ang-2." (PMID 32848510, 2020). "In this study, we analyzed CTHRC1 expression, prognostic value, genetic variations, and correlation with tumor immune cell infiltration in KIRP and KIRC for the first time." (PMID 33628726, 2020). "In GIST, CTHRC1 appears to activate the Wnt/PCP pathway in a dose-dependent manner, and Wnt5a/PCP-Rho axis determines the tumor invasion-promoting activity of CTHRC1." (PMID 32848510, 2020). "The correlation between CTHRC1 expression and tumor lymphocyte infiltration in human cancer (TISIDB)." (PMID 33628726, 2020). "The predictive model based on the CTHRC1 level and tumor angiogenesis markers can be used to predict LUAD patient prognosis more accurately." (PMID 31798347, 2019). "In contrast, CTHRC1 expression was very high in 55.2% of primary NSCLC tissues, and furthermore, CTHRC1 expression in NSCLC tissues was associated with tumour metastasis." (PMID 29631554, 2018). "The enhanced staining of CTHRC1 in tumor buds suggests a possible role of CTHRC1 in EMT and cancer metastasis." (PMID 30302922, 2018). "To further study the correlation between CTHRC1 and MMP7 as well as MMP9 in fresh primary tumour tissues, we measured the expression of CTHRC1 and MMPs by performing reverse dot blot hybridization." (PMID 29631554, 2018). "Given the role of CTHRC1 in the tumor invasion and metastasis, we made further efforts to identify the clinical significance of CTHRC1 for prognosis prediction in NSCLC patients." (PMID 29631554, 2018). "In total, we quantified approximately 4200 proteins and found that mucinous (e.g. MUC1 and MUC2) and mesenchymal proteins (such as THBS2, COL11A1, and CTHRC1) were significantly upregulated in the primary tumor compared to healthy surrounding tissue." (PMID 29901861, 2018). "Especially, the increased CTHRC1 staining was observed in the advancing front within tumor buds (arrows)." (PMID 30302922, 2018). "An adhesion assay demonstrated decreased tumour cell adhesion accompanying the ectopic overexpression of CTHRC1, while depletion of CTHRC1 increased tumour cell adhesion." (PMID 29631554, 2018).
tumor (continued). "The pattern of tumor formation in the peritoneal space was consistent with the phenotype observed in vitro, suggesting an important role of CTHRC1 in promoting metastatic character of EOC cell." (PMID 29021002, 2017). "Methylation array profiling of paired ESCC tissues revealed significantly lower methylation of cg07757887 (−1220 bp in the CTHRC1 genomic region) in ESCC tumour tissues compared with non-tumour tissues (n = 67, ∆ß =−0.19; FDR = 1.34E-23, unpublished data)." (PMID 28645305, 2017). "The IHC results showed a correlation between the expression of Wnt5a, Ror2 and CTHRC1 with high histological grade of the tumor, while E-cadherin showed an opposite trend of expression." (PMID 28427201, 2017). "Our data in the present study showed that the expression level of CTHRC1 in HCC tissue was notably higher than that in matched tumor-adjacent tissues, and its protein levels were also confirmed using IHC staining and the WB assay." (PMID 29234238, 2017). "Ectopic expression of CTHRC1 in HepG2 cells promoted cell migration and invasiveness in vitro, and promoted tumor metastasis in a lung metastasis mouse model." (PMID 29285247, 2017). "As expression of CTHRC1 was correlated with poor prognosis, our data also showed that CTHRC1 was highly expressed according to larger tumor size and worse differentiation." (PMID 29285247, 2017). "Since microRNAs are master regulators of gene expression and play important role in tumor progression, we sought to identify miRNAs that regulate CTHRC1 expression." (PMID 28697793, 2017). "A xenograft model was established to examine the effects of miR-155-5p and CTHRC1 on tumor formation." (PMID 29234238, 2017). "In this study, by using a microarray-based phosphor-antibody proteomics analysis, we distinguished a variety of proteins participating in tumor metastasis with phosphorylation that were down-regulated by the knockdown of CTHRC1." (PMID 29021002, 2017). "CTHRC1 mRNA was positively correlated with large tumor size (p <0.003), Edmondson differentiation grade (p <0.0001), microvessel invasion (p <0.05), intrahepatic metastasis (p <0.005), and HCC stage (AJCC, p <0.0001)." (PMID 29285247, 2017). "In comparison with the NC group, tumor growth was substantially elevated in the CTHRC1 group and notably suppressed in the miR-155-5p group." (PMID 29234238, 2017). "Taken together, these results support the notion that CTHRC1 expression is critical for cell proliferation and tumour growth both in vitro and in vivo." (PMID 28645305, 2017). "This is the first study to present a comprehensive set of clinical and experimental evidence establishing CTHRC1 as an oncogenic factor that facilitates ESCC tumour progression and metastasis, resulting in poor prognosis." (PMID 28645305, 2017). "Tumors from Panc-1/shCTHRC1-injected mice showed significantly decreased infiltration of TEMs compared with those from mice injected with Panc-1/shCON cells, indicating that CTHRC1-induced Ang-2 enhances infiltration of TEMs into tumor tissues." (PMID 27686285, 2016). "Immunofluorescence analyses showed that CTHRC1 overexpression is correlated with microvessel density in mouse tumor models." (PMID 27686285, 2016). "Previous reports have suggested that CTHRC1 secreted by tumor cells acts in an autocrine manner to modulate tumor progression and metastasis." (PMID 27686285, 2016). "Here we identified a novel role of CTHRC1 as a potent endothelial activator that promotes angiogenesis by recruiting bone marrow-derived cells to the tumor microenvironment during tumorigenesis." (PMID 27686285, 2016). "Of additional interest, the smallest control tumor with a high CTHRC1 expression showed high invasive capability (muscle invasion) and formed a rapidly growing secondary tumor (data not shown)." (PMID 26918341, 2016). "A further important step is to identify the mechanism or mechanisms of how CTHRC1 is regulated and its role in the tumor microenvironment." (PMID 27686285, 2016).
tumor (continued). "The CD45+ and CD31+ cell populations were significantly increased in tumor tissues from MiaPaCA-2/CTHRC1 cell-injected mice compared with those from mice injected with MiaPaCa-2/Mock cells, indicating that CTHRC1 has the potential to modulate vascularity." (PMID 27686285, 2016). "The population of TEMs (F4/80 and Tie2 double-positive cells) was increased in tumor tissues from mice injected with MiaPaCa-2/CTHRC1 cells compared with those from mice injected with MiaPaCa-2/Mock cells." (PMID 27686285, 2016). "A CTHRC1-neutralizing antibody, developed as a tool for functional studies, markedly reduced tumor growth and tumor vasculature in CTHRC1-expressing tumors." (PMID 27686285, 2016). "We found that OVCAR3/CTHRC1-siRNA cells predominantly localized to tumor nodules in the primary injection sites compared to control." (PMID 26452130, 2015). "We have assessed the correlation between CTHRC1 expression and EOC clinicopathological parameters and revealed that CTHRC1 levels were closely correlated with tumor size and clinical stage." (PMID 26452130, 2015). "In the univariate analysis, clinical stage, tumor grade and CTHRC1 levels were correlated with disease free survival of EOC patients (p = 0.001, 0.015 and < 0.001, respectively)." (PMID 26452130, 2015). "Forty-one surgically resected HCC specimens and adjacent non-tumor tissues were examined for CTHRC1 expression by immunohistochemistry." (PMID 24841500, 2014). "Verification of tumor responses to biologic agents according to the expression of CTHRC1 in vitro and vivo will be the next research step in the development of new treatment strategies based on such agents." (PMID 24504172, 2014). "In this study, we found that CTHRC1 expression was significantly increased in NSCLC cells and surgical tissues, and was closely associated with tumor metastasis." (PMID 25238260, 2014). "Previous studies have described several alternative functions of CTHRC1 in addition to signal transduction in tumor and vascular cells." (PMID 24504172, 2014). "Taken together, these results indicate that oncologic outcomes are worse in patients whose tumors express high levels of CTHRC1, which promotes invasivity of tumor cell via ERK-dependent induction of MMP9 expression." (PMID 24504172, 2014). "The expression profile and clinical importance of CTHRC1 were examined by reverse transcription-polymerase chain reaction and immunohistochemical analyses in normal and tumor patient samples." (PMID 24504172, 2014). "We were unable to detect Cthrc1 expression in any of the cancer cells themselves, but invariably observed Cthrc1 expression in stromal cells within the tumor or surrounding tumor cells." (PMID 24945147, 2014). "These cutoffs were set based on a consideration of median and average CTHRC1 expression in tumor tissues, respectively." (PMID 24504172, 2014). "Our results showed that CTHRC1 was overexpressed in HCC tissues compared with the surrounding non-tumor tissues." (PMID 24841500, 2014). "On the other hand, when CTHRC1 was overexpressed in Huh7 cells by retroviral transduction, invasiveness of the tumor cells was enhanced." (PMID 23922981, 2013). "Scratch wound assay also showed that closure of the wound was delayed in CTHRC1-knocked down HA22T cells, further confirming the effect of CTHRC1 on tumor cell migration." (PMID 23922981, 2013). "Suppression of CTHRC1 expression inhibited tumor migration and invasion whereas overexpression of CTHRC1 promoted tumor invasion." (PMID 23922981, 2013). "CTHRC1 is known to have an aberrant expression in many tumor types, such as cancers of the gastrointestinal tract, breast, lung and thyroid, but until now this marker was not investigated in differential diagnostics of NSCLC." (PMID 24299561, 2013). "In multivariate analysis of prognostic factors, only tumor stage and CTHRC1 expression were significant and independent prognostic factors for HCC patients." (PMID 23922981, 2013).